INS (insulin)
Diseases named in the same sentence as INS in open-access papers (continued):
Sharing a sentence is not in itself a finding about the gene and the disease.
diabetes (continued). "In addition, green tea has a hypoglycemic effect during diabetes by improving glucose tolerance and insulin sensitivity in murine models of diabetes, reducing hepatic glucose production and limiting intestinal glucose transport." (PMID 31690052, 2019). "In addition, BCAAs have been shown to modulate insulin secretion, except for insulin resistance, and another possible mechanism by which elevated BCAAs promote diabetes is via hyperinsulinemia leading to pancreatic beta cell dysfunction." (PMID 31827381, 2019). "Gene set analysis showed that insulin stimulation induced upregulation of genes involved in classical metabolic pathways, such as glycolysis, glucose metabolism, cholesterol biosynthesis, and genes regulated in diabetes in both Control and DKD AML12 cells." (PMID 30952843, 2019). "To study the developmental consequences of gestational hyperglycemia, we generated INSC93S transgenic pigs expressing mutant insulin (INS) C93S in pancreatic beta cells as a new model for mutant INS gene-induced diabetes of youth (MIDY) and characterized their glucose homeostasis during pregnancy." (PMID 31308048, 2019). "Therefore, the relationship between insulin and glucagon—the major factors that determine blood glucose level—is important in diabetes research." (PMID 31357734, 2019). "It should be noted that AZA/RES significantly increased IR expression in ASCsEMS II, which is consistent with the experiments conducted by other researchers, who found that RES considerably improved insulin sensitivity and glucose control in subjects with diabetes." (PMID 30370650, 2019). "Additionally, LAP provided the best discrimination accuracy for diabetes [area under the curve (AUC): 0.658 95% confidence intervals (CI) 0.645–0.671] and insulin resistance (AUC: 0.781 95% CI 0.771–0.792) when compared with other body adiposity parameters." (PMID 31297161, 2019). "The development of diabetes leads to a further increase of H2S that can inhibit insulin secretion and reduce the overload of diabetic beta cells by the reduction of the ATP content, activation of KATP channels, or inhibition of L-type voltage-dependent calcium channels." (PMID 31336965, 2019). "I tend to forget to take or skip my diabetes medication (e. g. insulin, tablets)." (PMID 31938590, 2019). "These receptors are also involved with the regulation of body weight and intermediate metabolism, as well as insulin secretion, and may be responsible for the adverse effects of weight gain and diabetes." (PMID 31478094, 2019). "Similarly, findings from the Dutch Diacourse study, indicated worse diabetes-related distress among people receiving insulin therapy.." (PMID 31796044, 2019). "Diabetes is part of a group of metabolic disorders characterized by long-term high blood glucose levels due to either inadequate production of insulin (type 1) or poor response of the recipient cell to insulin (type 2)." (PMID 31398847, 2019). "Gene expression data from the same individuals indicates that miRNAs whose expression is associated with HbA1c may also regulate the expression of their targets in the insulin signaling and type 2 diabetes mellitus pathway." (PMID 31222113, 2019). "Moreover, diabetes therapeutic medicines such as pioglitazone improve insulin tolerance, and GLP-1 improves diabetes." (PMID 31374892, 2019). "Furthermore, diabetes onset is preceded by an increased number of circulating autoreactive T cells and autoantigens, including the most important ones to (pro) insulin, GAD65, IA-2, and others." (PMID 31139178, 2019). "This evidence indicates BK channels play a critical role in insulin-induced increases in glomerular barrier permeability and might participate in podocyte injury and proteinuria in diabetes." (PMID 30873046, 2019).
diabetes (continued). "Latent autoimmune diabetes in adults (LADA) is an autoimmune disease characterized by onset in adults and the presence of diabetes-associated autoantibodies but no requirement for insulin treatment for a period (usually six months) after diagnosis." (PMID 31540313, 2019). "43.8% (n = 111) took medication for diabetes; in 21.3% (n = 55), the medication was insulin." (PMID 31218230, 2019). "Our data highlight poor glycaemic control regardless of insulin delivery method, high rates of non-attendance, and other adverse cardio-metabolic risk factors among 18–25 years old with diabetes." (PMID 30574663, 2019). "Therefore, combined treatment using DPP-4 inhibitors plus insulin is a potentially effective treatment approach for patients with poor diabetes control." (PMID 30611254, 2019). "Type 2 diabetes mellitus (T2DM) is the most common endocrine and metabolic disease, which is characterized by high blood glucose, insulin resistance, and a relative deficiency of insulin." (PMID 32010641, 2019). "Finally, B lymphocyte capacity to act as APCs in autoimmune diabetes environment was tested by analyzing the ability of these cells to present a known diabetes-related autoantigen, known as 2.5HIP, a Hybrid Insulin Peptide." (PMID 31428087, 2019). "Therefore, replacement of pancreatic β-cells is a logical strategy for the treatment of diabetes, and the generation of insulin-producing cells (IPCs) from stem cells has been widely investigated as an alternative source for pancreatic β-cells." (PMID 31839754, 2019). "A disturbance in the insulin metabolism leads to diabetes mellitus." (PMID 31387633, 2019). "Infusion of animal-based amino acids induces insulin resistance with phosphorylation of downstream factors involved in insulin-signaling cascade and therefore animal-protein diets, e.g., the hospital diet, may increase insulin resistance and diabetes risks." (PMID 31461862, 2019). "The differences in postprandial incretin and insulin secretion identified in this study suggest that longer-term studies would be beneficial to show if a vegan diet may prevent the development of diabetes or slow down diabetes progression." (PMID 30813546, 2019). "Subgroup analysis comparing T2D on OAD alone with T2D on insulin showed that both groups were similar in term of symptoms at presentation, demographic (gender, the age of diagnosis and duration of diabetes), family history, body mass index (BMI), lipid and blood pressure profiles." (PMID 30682116, 2019). "In our study, 18% (n=54) were totally unwilling to start insulin, 38% (n=113) thought that insulin interferes and restricts their social life and 78% (n=233) have perception that insulin is the last resort to cure diabetes and once started has to be taken for whole life." (PMID 30881393, 2019). "Diabetes mellitus is a chronic disorder that occurs either because of the inability of the pancreas to produce adequate amounts of insulin or its failure to utilize available insulin efficiently." (PMID 31737067, 2019). "Individuals with prediabetes can be as insulin-resistant as individuals with diabetes." (PMID 30992067, 2019). "All these data indicate that a few factors may influence the increase in glycemia after the meal, which creates significant practical difficulties in determining the appropriate dose of insulin to compensate for food intake in people with diabetes." (PMID 30871141, 2019). "According to the type of an abnormal insulin, diabetes mellitus is divided into two types." (PMID 31316568, 2019). "Intestinal cells apoptosis were checked by tunnel assay, Incretin hormones secretion and dipeptidyl peptidase 4 (DPP-IV) activity were analyzed through ELISA and immunohistochemistry was used to determine the insulin expression of intestine at different time interval during diabetes progression." (PMID 31380261, 2019).
diabetes (continued). "Diabetes Mellitus is a cluster ofmetabolic disorder, an illness of hyperglycemia in which persongrieves from disorders like failure of pancreas to produce insulin orinsensitivity of cells towards insulin (insulin resistance)." (PMID 31354193, 2019). "Our findings could lead to the proof of concept to develop combination therapy (insulin and galangin) for the potential treatment of diabetes mellitus and as well, improve skeletal muscle cell health." (PMID 30862104, 2019). "Additionally, in the subgroup analysis, “other diabetes treatments” included not only patients who were on other oral agents, but also those on insulin." (PMID 31139216, 2019). "Type 1 diabetes mellitus (T1DM) is an autoimmune disease, and due to the gradual destruction of β-cells by T-cell, T1DM is characterized by deficiency or insufficiency of insulin in peripheral targets, hyperglycemia, metabolic and neural diseases, and a shorter life span." (PMID 31231496, 2019). "Vitamin D might contribute in ameliorating diabetes complications not only by improving blood glucose and insulin levels, but also by suppressing AGER and OGT gene expression in the liver." (PMID 31231498, 2019). "Agents used for the treatment of diabetes must address these recognized pathophysiologic inflammatory mechanisms (inflammation, epigenetic changes, insulin resistance, fuel excess, and abnormal metabolic environment) that have been identified in other organ injury that parallels the retina." (PMID 31920963, 2019). "Therefore, we evaluated the effects of the interactions between GCK and INSR single-nucleotide polymorphisms (SNPs) and chronic heavy alcohol consumption on β-cell function, insulin sensitivity, and development of diabetes in a 12-year follow-up cohort study." (PMID 31882596, 2019). "Taken together and acknowledging potential bias associated with observational studies (including a more severe diabetes phenotype as indicated by a higher use of insulin in metformin users), these findings challenge reports of an acute infarct-sparing role for metformin." (PMID 31815634, 2019). "While many upstream factors may modify Aβ toxicity, our results suggest that insulin signaling is the main downstream executor of Aβ damage, and thus may serve as a promising target for Alzheimer’s treatment in non-diabetes patients." (PMID 30652125, 2019). "The spectrum of diabetes treatment modalities was diverse, with 1540 (53.3%) using only oral antidiabetic medication, 365 (12.6%) only insulin, 61 (2.1%) other injectable antidiabetic drugs (GLP-1 receptor agonists) and 577 (20.0%) taking combinations of oral and injectable drugs." (PMID 30897159, 2019). "The treatment of diabetes depends on insulin injections, diet, and exercise." (PMID 31231500, 2019). "The insulin-induced increase of GPAT1 mRNA results from the activation of SREBP-1c because insulin increases SREBP-1c mRNA in the livers of rats with streptozotocin-induced diabetes." (PMID 30813330, 2019). "With the increase in the prevalence of diabetes and need for insulin, and the limited sources of supply, smaller markets may suffer." (PMID 31551632, 2019). "For cluster 3, a total of 29 significantly enriched pathways were identified, and several pathways were associated with diabetes, including insulin signaling pathway, insulin resistance, glycolysis/gluconeogenesis, FoxO signaling pathway, HIF-1 signaling pathway, and type 2 diabetes mellitus." (PMID 31338039, 2019). "In clinical treatments, Rosiglitazone is an agonist of PPARγ that could ameliorate the memory of Alzheimer patients and even increase insulin sensitivity for diabetes." (PMID 31652794, 2019). "Effective decision making about correct insulin dose may delay or prevent diabetes complications, such as heart attack, kidney disease, blindness, and amputation." (PMID 31464196, 2019). "Reduced dietary intake of carrageenan may lead to improved insulin sensitivity and inhibit development of diabetes." (PMID 31179345, 2019).
diabetes (continued). "The frequent injection of exogenous insulin is the major treatment of diabetes." (PMID 30893913, 2019). "Age, insulin dose, mistimed insulin doses, low body mass index, impaired renal function, and changes in diet or concomitant medications such as steroids are all potential contributing factors to hypoglycemic episodes among hospitalized patients with diabetes." (PMID 31775749, 2019). "Many eHealth interventions (e.g., mobile Apps for diabetes) offer glucose, food and insulin diaries with little perceived value in return which could lead to sub-optimal user-engagement." (PMID 30889802, 2019). "If the patient also has diabetes mellitus requiring high insulin doses, severe hypertriglyceridemia, nonalcoholic steatohepatitis, or polycystic ovarian syndrome (PCOS), lipodystrophy may be further indicated." (PMID 29704234, 2019). "Diabetes is a variety of metabolic diseases in which individualsare unable to produce or uptake adequate levelsof insulin, resulting in high levels of blood glucose.Diabetes mellitus could deregulate a variety of cellularand molecular pathways." (PMID 30291688, 2019). "However, left atrial size was lowest in diabetes patients treated with insulin compared to the other two groups." (PMID 31271255, 2019). "Nearly half of the patients had diabetes complications that were associated with a negative attitude towards insulin therapy." (PMID 31368319, 2019). "Diabetes is a disease that can be treated with oral antidiabetic agents and/or insulin." (PMID 31814880, 2019). "Similarly, renin inhibition with aliskiren improves insulin sensitivity, skeletal muscle glucose uptake, glucose tolerance, and insulin secretion in male rodent models of hypertension, diabetes, obesity, and metabolic syndrome." (PMID 31262355, 2019). "Costs considered for DM care included the costs of insulin treatment, consultations with endocrinologists, diabetes specialist nurse services, diabetes education, gastrointestinal examinations, dietician appointments and inpatient care for ketoacidosis and severe hypoglycaemic events." (PMID 31366393, 2019). "KRG-mediated health-improving effects such as anti-cancer, anti-diabetes, and anti-inflammation effects have been reported to be related to the insulin/IGF-1 signaling (IIS) pathway, and downregulation of IIS has been reported to increase lifespan in many model organisms." (PMID 31672931, 2019). "Diabetes (diabetes mellitus) is a heterogeneous group of disorders characterized by hyperglycemia that results from a complete or relative insufficiency of insulin secretion and/or insulin action." (PMID 31197747, 2019). "Furthermore, anti-insulin B cell depletion using the mAb123 antibody in NOD mice protected against spontaneous diabetes." (PMID 31444529, 2019). "Compared with patients without diabetes, patients on insulin had a substantially higher risk of sudden death (fully adjusted HR 2.55; 95% CI 1.93–3.37; P < 0.001) as well as pump failure death (fully adjusted HR 2.14; 95% CI 1.47–3.11; P < 0.001)." (PMID 31271255, 2019). "Besides regulating growth, IGF binding proteins influence metabolism through the binding to IGFs and thereby manipulate glucose and insulin levels and are central players in diabetes, obesity and other metabolic diseases." (PMID 31022261, 2019). "Knowledge and attitude of patients regarding insulin self-administration could lead to better management of diabetes and eventually a good quality of life." (PMID 31915711, 2019). "The results revealed that diabetes caused testicular stereological changes and significantly increased blood glucose level, testicular MDA content and apoptosis but decreased insulin level, testicular GPX activity, and sperm parameters compared to controls (p<0.001 to p<0.05)." (PMID 31309075, 2019).
diabetes (continued). "Diabetes mellitus is a metabolic disorder of multiple etiology characterized by chronic hyperglycaemia with disturbances of carbohydrate, fat and protein metabolism resulting from defects in insulin secretion, insulin resistance, or both." (PMID 30630432, 2019). "This occurred because diabetes control improved or because insulin was initiated instead." (PMID 31261613, 2019). "However, treated for 4 weeks by CEC (DM + CEC) group (29 ± 7.14 pmol/L) significantly increased the insulin level when compared to untreated-diabetes (DM) group." (PMID 31645652, 2019). "However, there remain several issues that should be addressed before accepting the suitability of intranasal delivery of insulin in diabetes therapy." (PMID 31210056, 2019). "An integrated tele-health intervention delivered via Facebook group “Diabetes Macedonia” leveraged patients and caregivers education along with tailored treatment plans including pump setting, basal bolus insulin delivered via skype using the data uploaded by patients." (PMID 31752801, 2019). "Diabetes mellitus (DM) describes a metabolic disorder of multiple etiologies characterized by chronic hyperglycaemia with disturbances of fat, protein and carbohydrate metabolism due to impairment in insulin secretion, insulin action, or both." (PMID 31304013, 2019). "Diabetes mellitus is a metabolic and/or hormonal condition that is usually described by persistent hyperglycemia, as a result of defects in insulin secretion by pancreatic β-cells, and reduced sensitivity of cell surface receptors to insulin or both." (PMID 31118963, 2019). "However, in people with diabetes, the most significant determinants of albuminuria were the duration of diabetes, HbA1c and the use of insulin." (PMID 30799525, 2019). "Treatment of diabetes with insulin was not statistically associated with dry eye in this study, (p = 0.1367)." (PMID 31312330, 2019). "Diabetes mellitus (DM) is a chronic condition that occurs when there are raised levels of glucose in the blood because the body cannot produce any or enough of the hormone insulin or use insulin effectively." (PMID 31198788, 2019). "Increased fatty acids inhibit insulin signaling by altering Akt and protein tyrosine phosphatase 1B-dependent pathways, which is considered a potential mechanism for insulin resistance and cardiovascular complications in diabetes." (PMID 31443411, 2019). "Therefore, new strategies for insulin and insulin analogs production are urgently required to improve low-cost access to therapeutic products, so as to contain the diabetes epidemic." (PMID 31798448, 2019). "There were 206 (42%) diabetes patients on insulin treatment." (PMID 31271255, 2019). "Among the various treatment strategies, diet therapy, pharmacotherapy, and insulin therapy are the main treatment options available to control diabetes, in addition to wide range of glucose lowering drugs which exert their hypoglycemic effects through various mechanisms." (PMID 31708869, 2019). "Insulin is recommended to treat hyperglycaemia in the global guideline of pregnancy and diabetes." (PMID 30957612, 2019). "Of 8466 patients, 2653 (31%) had diabetes, including 979 (37%) receiving insulin." (PMID 31271255, 2019). "High glucose-induced oxidative stress in diabetes would affect the regulation of insulin, which may lead to a reduction in insulin synthesis and promote β cell dysfunction." (PMID 31228042, 2019). "In this study, we found that remission of T2D after bariatric surgery was inversely associated with duration of diabetes and was highest among patients with recent onset and those without insulin treatment." (PMID 31747392, 2019). "Treatment with insulin and combination of insulin therapy and oral medication was associated with worse HRQOL in the domain of other health problems and diabetes complications and in perception of overall severity of diabetes." (PMID 31796044, 2019).